KIT (KIT proto-oncogene, receptor tyrosine kinase)
Diseases named in the same sentence as KIT in open-access papers (continued):
Sharing a sentence is not in itself a finding about the gene and the disease.
brain tumors (10 papers, 2010 to 2026). "Myeloid-derived suppressor cells (MDSCs), macrophages, and regulatory T cells were increased in brain tumors implanted with KIT-HA GL261." (PMID 41688273, 2026). "Researchers have also examined KIT expression in 35 pilocytic astrocytomas and 45 other pediatric brain tumors using immunohistochemistry." (PMID 23717811, 2013). "KIT was also found in the endothelial cells of pediatric brain tumors, and was more common in pilocytic astrocytomas diagnosed at a young age." (PMID 23717811, 2013). "Graded co-expression of KIT and Zonulin (marker for degraded blood brain barrier) in different grades of brain tumors (5 GBMs and one case each of astrocytoma WHO III and meningioma WHO III) was reported earlier." (PMID 22672386, 2012). "Recent findings suggest that the SCF/KIT signaling plays an important role in angiogenesis of brain tumors and also of histologically normal tissues." (PMID 20030644, 2010). "Some pediatric tumors express KIT 2, 23, but little is known about expression or the role of endothelial cell KIT in pediatric brain tumors." (PMID 20030644, 2010). "KIT and phospho‐KIT were present in endothelia of other pediatric brain tumors, notably ependymomas." (PMID 20030644, 2010). "Sunitinib malate is a small multi‐targeted tyrosine kinase inhibitor that inhibits vascular endothelial growth factor receptor (VEGFR), platelet‐derived growth factor receptor (PDGFR) and stem cell factor receptor (KIT), which are highly expressed by some high‐grade brain tumors." (PMID 27109549, 2016). "We conclude that KIT is commonly present in the endothelial cells of brain tumors in children." (PMID 20030644, 2010). "We conclude that KIT is commonly present in endothelial cells of juvenile brain tumors and thus may play a role in angiogenesis in these neoplasms." (PMID 20030644, 2010). "Taken together, these findings suggest that endothelial cell KIT may have a role in angiogenesis of brain tumors, and possibly of other types of human tumors and normal tissues as well." (PMID 20030644, 2010). "Thus, presence of KIT and activated KIT in brain tumor microvessels of young children might reflect KIT expression in the endothelial cells of normal brain tissue in the fetus and young children." (PMID 20030644, 2010). "The PERK inhibitor GSK2606414 blocks brain tumor cell migration, but this inhibitor is also known to target RIPK1 and c-KIT." (PMID 31064137, 2019). "In the present study we investigated expression of tumor and intratumoral vessel endothelial cell KIT, SCF and vascular endothelial cell growth factor receptor‐2 (VEGFR‐2) in pilocytic astrocytomas and other pediatric brain tumors." (PMID 20030644, 2010). "Tumor endothelial cell expression of KIT, phosphorylated KIT, SCF and VEGFR‐2 in 84 pediatric brain tumors." (PMID 20030644, 2010). "To investigate whether tumor endothelial cells might express KIT, SCF or VEGFR‐2 also in other types of pediatric brain tumors than pilocytic astrocytoma, we examined 49 further tumors with immunohistochemistry." (PMID 20030644, 2010). "Tumor cell expression of KIT, phosphorylated KIT, SCF and VEGFR‐2 in 84 pediatric brain tumors." (PMID 20030644, 2010). "We assessed expression of KIT, phosphorylated KIT, stem cell factor (SCF) and vascular endothelial growth factor receptor‐2 (VEGFR‐2) in 35 juvenile pilocytic astrocytomas and 49 other pediatric brain tumors using immunohistochemistry, and KIT messenger RNA (mRNA) using in situ hybridization." (PMID 20030644, 2010).
COVID-19 (10 papers, 2020 to 2025). A disease caused by infection with severe acute respiratory syndrome coronavirus 2. "Regarding mastocytes, lung biopsies have shown an abundant infiltrate of KIT+ cells in COVID-19 patients and SARS-CoV-2-infected African green monkeys, suggesting the early recruitment of mastocyte progenitors to the alveolar septa." (PMID 36012423, 2022). "In pre-DCs, an up-regulation of the stem cell marker c-KIT was detected in severe COVID-19, and AXL was decreased in response to infection." (PMID 33479167, 2021). "When investigating the phenotype of DC1, a minor expansion of AXL+DC1, possibly related to type-I IFN signaling, was a general feature in COVID-19 along with decreased expression of the differentiation marker c-KIT." (PMID 33479167, 2021). "However, to the best of our knowledge, the serum levels of KIT have not yet been associated with COVID-19 patient outcomes." (PMID 36012423, 2022). "Enrichment of IL-20, IL-2, IL-6, KIT, and JAK-STAT signaling pathways was unique to monocytes and DCs from patients with COVID-19, suggesting that innate immune cells may be much more active and cytotoxic in COVID-19 compared to in HIV-1." (PMID 36992700, 2023). "Interestingly, other MC-specific genes, such as SIGLEC6, HDC, KIT, and others were not increased in COVID-19 lung tissue." (PMID 33777047, 2021).
papillary thyroid carcinoma (10 papers, 2012 to 2023). "Moreover, we performed functional studies on human papillary thyroid carcinoma cell line to associated c-KIT expression to thyrocytes differentiation and tumor proliferation." (PMID 28301608, 2017). "A low expression of c-KIT gene has been reported during the transformation of normal thyroid epithelium to papillary carcinoma suggesting a possible role of the gene in the differentiation of thyroid tissue rather than in the proliferation." (PMID 22233760, 2012). "For instance, the PKI sorafenib inhibits the kinases RAF, BRAF, FLT3, VEGFR 1–3, PDGFR, c-KIT and RET and significantly improves progression-free survival compared with placebo in patients with progressive radioactive iodine-refractory differentiated thyroid cancer." (PMID 34888523, 2021).
serous ovarian carcinoma (10 papers, 2004 to 2025). "We analysed the expression of KIT and PDGFRA by immunohistochemistry in 522 serous ovarian carcinomas, and mutations of KIT and PDGFRA by denaturing high-performance liquid chromatographyin 125 and 187 serous ovarian carcinomas, respectively." (PMID 15583695, 2004). "We found the expression of KIT protein in 12% of serous ovarian carcinomas: 10% showed low and 2% high expression of the protein." (PMID 15583695, 2004). "KIT immunostaining was interpretable in 516 (99%) of the 522 serous ovarian carcinomas." (PMID 15583695, 2004). "No KIT or PDGFRA mutations were found in serous ovarian carcinomas." (PMID 15583695, 2004). "However, in our study, both KIT and PDGFRA expression were associated with aggressive tumour characteristics, such as high tumour grade, high proliferation index and poor patient outcome, suggesting them a role in the pathophysiology of at least a subset of serous ovarian carcinomas." (PMID 15583695, 2004). "Protein expression status of KIT and PDGFRA was performed by immunohistochemistry of tissue microarray containing 522 serous ovarian carcinomas." (PMID 15583695, 2004). "The lack of KIT and PDGFRA mutations seems discouraging as regards potential usefulness of imatinib mesylate in serous ovarian carcinoma." (PMID 15583695, 2004). "In conclusion, no mutations of KIT or PDGFRA were found, but a subset of serous ovarian carcinoma showed overexpression of the proteins, which was associated with aggressive tumour characteristics." (PMID 15583695, 2004).
testicular cancer (10 papers, 2004 to 2025). A primary or metastatic malignant neoplasm that affects the testis. "The risk factors for testicular cancer include genetic risk factors (especially mutations in the KIT and RAS genes), environmental exposures and underlying disorders (e.g., cryptorchidism, hypospadias and impaired spermatogenesis)." (PMID 38188291, 2023). "In a previous analysis of molecular alterations of testicular cancer tumors in The Cancer Genome Atlas (TCGA), the authors identified that somatic mutations of three genes—KIT, KRAS, and NRAS—were commonly observed in testicular cancers." (PMID 34819066, 2021). "Exons 10, 11 and 17 of KIT were examined for somatic mutations in 123 TGCT from 93 multiple-case testicular cancer families." (PMID 15150569, 2004). "In particular, KIT gene variants might be the determinants in the association between this condition and testicular cancer." (PMID 37109682, 2023). "Genetic risk factors, especially mutations in the KIT and RAS genes, are also risk factors for testicular cancer." (PMID 38188291, 2023). "Other gene mutations associated with testicular cancer are those related to KRAS and KIT." (PMID 37109682, 2023). "Among 25 hub genes, EFTUD2, HNRNPD, KIT, NCL and RPS8 were significantly upregulated in testicular cancer patients, however, ELAVL2 and NRXN1 were significantly downregulated using GEPIA online database." (PMID 33746583, 2021). "As expected, EFTUD2, ELAVL2, HNRNPD, KIT, NCL, NRXN1 and RPS8 were significantly varied in testicular cancer patients." (PMID 33746583, 2021). "Mutations in KIT signalling and continued KIT expression are seen in CIS cells, but not more advanced stages of testicular cancer, indicating that this may be an initial feature of CIS cell specification." (PMID 24555040, 2013).
yolk sac tumor (10 papers, 2007 to 2025). A non-seminomatous malignant germ cell tumor composed of primitive germ cells. "An analysis of 87 MOGCTs identified recurrent mutations in KIT and KRAS, along with frequent focal amplifications of PIK3CA and AKT1 in yolk sac tumors." (PMID 32455595, 2020).
Hypertension (9 papers, 2012 to 2025). The presence of chronic increased pressure in the systemic arterial system. "Furthermore, both drugs suffer from a poor kinase selectivity profile, leading to hand-foot syndrome related to multitargeted tyrosine kinase inhibition, overlapping hematopoietic toxicities due to dual inhibition of FLT3 and KIT and high-grade hypertension linked to VEGFR2 inhibition." (PMID 40018846, 2025). "Previous clinical studies have shown that cabozantinib toxicity, which mainly manifests as diarrhoea, nausea, fatigue, decreased appetite, hand–foot syndrome and hypertension is due to the direct inhibition of VEGFR, FLT3 and KIT kinases, primary cabozantinib targets." (PMID 40437874, 2025). "In univariate analysis two factors significantly correlated with shorter PFS and OS that were: tumor genotype: exon 11 KIT or PDGFRA mutation (p = 0.04 and p = 0.04, respectively), and absence of arterial hypertension during sunitinib therapy (p = 0.0001 and p = 0.001)." (PMID 22439647, 2012).
paraganglioma (9 papers, 2012 to 2025). A benign or malignant neoplasm arising from paraganglia located along the sympathetic or parasympathetic nerves. "Another scenario where the patient can have GIST at multiple sites includes patients with family history of GIST and germline KIT mutations in patients with Carney’s triad and a distinctive syndrome characterized by multicentric paragangliomas and GIST." (PMID 35490251, 2022). "Our cluster analysis shows a separation of SDH-deficient GISTs together with pheochromocytoma/paraganglioma from KIT-mutant GISTs, suggesting that this pattern is common to tumors sharing a deficiency of the succinate dehydrogenase complex." (PMID 33806389, 2021). "SDH-deficient GISTs and pheochromocytoma/paraganglioma were distinctly separate from KIT-mutant GISTs, suggesting that the EMT expression pattern represents a shared feature in SDH-deficient tumors and is clearly different to KIT-mutant GISTs." (PMID 33806389, 2021). "Similarly to the EMT and hedgehog pathways, we showed that genes related to hypoxia signaling produced clusters combining SDH-deficient GISTs with pheochromocytoma/paraganglioma and separating them from KIT-mutant GISTs." (PMID 33806389, 2021). "NMU expression in NB is significantly higher than in pheochromocytomas, paragangliomas, or normal adrenal glands; it correlates with KIT expression and is associated with a poor outcome, which suggests that it is a novel prognostic factor associated with KIT expression in NB." (PMID 31681584, 2019). "Indeed, it was shown that mutations in SDHA account for around 30% of all KIT/PDGFRA-WT GIST, while being responsible for <1% of all pheochromocytoma and paraganglioma cases (PPGL), as opposed for example to SDHB that accounts for about 10% of all PPGL." (PMID 35059314, 2021). "Additionally, no somatic drivers were identified in the pheochromocytoma and paraganglioma, nor were any pathogenic variants in KIT or PDGFRA detected in the GIST." (PMID 40242210, 2025). "The best known association between SDH complex II germline mutations and other tumors is represented by the Carney–Stratakis syndrome (or dyad) which is characterized by the occurrence of KIT and PDGFRA WT GIST and paraganglioma." (PMID 22974104, 2012).
phyllodes tumor (9 papers, 2013 to 2025). A benign, borderline, or malignant fibroepithelial neoplasm arising from the breast and rarely the prostate gland. "Other genetic abnormalities in phyllodes tumor that have been described in the COSMIC database (as of February 2013) are CDKN2A mutation (1/25 ptes), KIT mutation (1/26 ptes), and PI3KCA mutation (1/1 pte)." (PMID 23895135, 2013).
Splenomegaly (9 papers, 2011 to 2025). Abnormal increased size of the spleen. "Concordantly, studies describing KIT mutations have associated splenomegaly with occurrence of mutations." (PMID 36357474, 2022). "These include, among others, multi-lineage involvement of hematopoietic cells with KIT D816V, the variant allele frequency (VAF) of mutated KIT, an elevated β2-microglobulin, elevated alkaline phosphatase levels, lymphadenopathy and splenomegaly, and the presence of additional somatic mutations." (PMID 31216696, 2019). "In addition to sBT, the presence of hepatomegaly plus splenomegaly also emerged as an independent predictor for multilineal KIT mutation, and only this subset of multilineal cases developed diffuse bone sclerosis; these results suggest the existence of a close association between these two features." (PMID 24155887, 2013). "B-findings (splenomegaly and a high KIT D816V VAF) were finally proven corresponding to evolving SSM." (PMID 40963125, 2025). "In addition, new splenomegaly and a high variant allele frequency (VAF) of 22% for KIT D816V in peripheral blood represented two B-findings indicating a transition to SSM." (PMID 40963125, 2025). "In addition, patients homozygous for the KIT M541L variant did not have a history of splenomegaly and less splenomegaly was seen in the heterozygous group, although not significant." (PMID 39037378, 2024). "In addition, the homozygous group with the KIT M541L on both alleles had less splenomegaly compared to the other groups, however, none of these differences reached significance." (PMID 39037378, 2024).
teratoma (9 papers, 2005 to 2025). A non-seminomatous germ cell tumor characterized by the presence of various tissues which correspond to the different germinal layers (endoderm, mesoderm, and ectoderm). "On the other hand, a strong expression of KIT was observed in a partially keratinised epithelial component of teratoma." (PMID 15856041, 2005). "In the biopsy group, c-KIT expression was as follows: 9 (40%) of 22 SEM [9 (45%) of 20 diffuse SEM, 0 (0%) of 2 intratubular SEM], 1 (6%) of 16 SCT, 1 (100%) of 1 teratoma, and 4 (100%) of 4 mixed LCT/SEM." (PMID 25096628, 2014). "The KIT protein is in most cases found expressed in CIS and SEM, but not in N-SEMs, with an exception of undifferentiated somatic elements that sometimes can be present in teratomas." (PMID 15856041, 2005).
vitiligo (9 papers, 2015 to 2025). Generalized well circumscribed patches of leukoderma that are generally distributed over symmetric body locations and is due to autoimmune destruction of melanocytes. "It is known that in the melanocytes of vitiligo involved skin, the expression level of KIT is decreased and can be associated with the dysfunction and/or loss of these cells." (PMID 34884858, 2021). "The numbers of melanocytes expressing KIT protein receptor in the skin of patients with vitiligo is lower, indicating that the expression of KIT is related to melanocytes." (PMID 32596061, 2020). "Intriguingly, we also observed increased KIT signaling in lesional skin, suggesting that loss of this melanocyte homeostatic signal alone is not responsible for the failure of chronic vitiligo lesions to repigment." (PMID 35653192, 2022). "Furthermore, KIT is the master regulator of melanocyte differentiation, accordingly KIT inhibitors induce vitiligo and hair color changes." (PMID 36213163, 2022).
acute lymphoblastic leukemia (8 papers, 2017 to 2025). Leukemia with an acute onset, characterized by the presence of lymphoblasts in the bone marrow and the peripheral blood. "Dasatinib is an orally available TKI of ABL1, SRC family kinases, KIT, and PDGFRα/β, and has been approved for the treatment of chronic myeloid leukemia (CML) and Philadelphia-chromosome-positive acute lymphoblastic leukemia (Ph+ ALL)." (PMID 34207383, 2021).
Arthritis (8 papers, 2010 to 2025). Inflammation of a joint. "The mechanism of action of imatinib in these settings remains largely unknown, but multiple lines of evidence indicate that the drug can inhibit diverse cellular responses that play critical roles in driving arthritis, including inhibition of mast cell activation (via its effects on KIT)." (PMID 28982129, 2017). "These mice showed resistance to arthritis or full development of arthritis, which may attribute to the depletion of other hematopoietic and non-hematopoietic cells expressing KIT." (PMID 38168103, 2024).
chronic eosinophilic leukemia (8 papers, 2015 to 2025). "Patients with chronic eosinophilic leukemia positive for KIT p.M541L showed clinical response to low dose imatinib." (PMID 26887047, 2016). "Moreover, in four cases we found the c.1621A>C (M541L) variant of KIT, which has been shown to be associated with chronic eosinophilic leukemia, not otherwise specified." (PMID 33791220, 2021).
cutaneous mastocytosis (8 papers, 2015 to 2025). Cutaneous mastocytosis is a term referring to a group of diseases characterized by abnormal accumulation and proliferation of skin mastocytes. "Cutaneous mastocytosis arises from abnormal accumulation of mast cells in the skin, driven by mutations such as KIT D816V in some cases." (PMID 40585443, 2025). "Other isolated relatives carrying the KIT germline variant have manifested cutaneous lesions- such as cutaneous mastocytosis and dermatofibroma (IV-3), and two other relatives (I-4) and (II-6) had histories suggestive of GISTs." (PMID 38538628, 2024). "DNA sequencing identified a pathogenic, heterozygous variant in the KIT gene NM_000222.3:c.1504_1509dup; p.(Ala502_Tyr503dup), previously associated with cutaneous mastocytosis." (PMID 38002964, 2023). "The typical driver mutation for cutaneous mastocytosis is in the KIT gene." (PMID 38002964, 2023). "A prospective cohort of 68 children from a referral center in Slovenia with cutaneous mastocytosis (CM) underwent tryptase genotyping by droplet digital PCR and examination for KIT p.D816V in PBL using a sensitive PCR test." (PMID 40649802, 2025). "Data from a phase 2 study in patients with systemic or cutaneous mastocytosis (N = 25) treated with the KIT/LYN kinase inhibitor masitinib, however, demonstrated an ORR of 56.0 % and modest improvements in symptoms and quality-of-life measurements after 12 weeks of treatment." (PMID 26002753, 2015).
endometriosis (8 papers, 2015 to 2024). The growth of functional endometrial tissue in anatomic sites outside the uterine body. "Increased concentrations of SCF as well as c-KIT were described in peritoneal fluid and ectopic implants of endometriosis patients." (PMID 36612107, 2022). "Additionally, treatment with pexidartinib decreases inflammatory signaling and cell survival in endometriosis by suppressing macrophage-colony stimulating factor 1 receptor and stem cell growth factor receptor KIT." (PMID 38698459, 2024).